SDC1 (syndecan 1)
Diseases named in the same sentence as SDC1 in open-access papers (continued):
Sharing a sentence is not in itself a finding about the gene and the disease.
Sepsis (continued). "Furthermore, elevated plasma syndecan-1 levels have been associated with increased mortality in patients with trauma and sepsis." (PMID 28986821, 2017). "Our data indicate a high level of Syndecan-1 is associated with increased mortality, and is associated with increased levels of thrombomodulin, pro-inflammatory cytokines, hsCRP, and procalcitonin, which suggests the presence of serious endothelial damage, inflammation, and sepsis in these patients." (PMID 34861818, 2021). "Seven biomarkers indicating endothelial dysfunction (mid‐regional proadrenomedullin (MR‐ProADM), syndecan 1, thrombomodulin, angiopoietin 2, endothelial cell‐specific molecule 1, vascular cell adhesion molecule 1 and E‐selectin) had stronger associations with sepsis than infection alone." (PMID 32073224, 2020). "Together, these findings suggest that measurement of syndecan-1 levels in patients with sepsis may be useful for identifying patients at high risk of organ dysfunction and mortality and those who may benefit from therapies targeted at protecting or restoring the glycocalyx." (PMID 28986821, 2017). "Prior studies have consistently linked elevated syndecan-1 and MMP-9 levels to adverse outcomes and multi-organ dysfunction in sepsis." (PMID 40766307, 2025). "We examined the recovery of sepsis-associated DIC and fluctuations in serum syndecan-1 levels according to the JAAM-DIC criteria." (PMID 40740948, 2025). "Recent reports have shown that serum syndecan-1 levels are correlated with sepsis severity, organ dysfunction, and mortality in patients with sepsis." (PMID 40740948, 2025). "In a study of patients undergoing abdominal surgery, patients suffering from sepsis had a higher Syndecan-1 concentration in blood on the first postoperative day than non-septic patients." (PMID 40943808, 2025). "Syndecan-1, a biomarker of endothelial glycocalyx injury, has been proposed as a potential indicator of sepsis severity and prognosis." (PMID 40740948, 2025). "In an animal study, UFH treatment significantly reduced the levels of inflammatory biomarker syndecan-1 (SDC-1) and heparan sulfate in LPS-induced sepsis rat models." (PMID 40083381, 2025). "Relationship between recovery from sepsis-associated DIC at the end of anticoagulant therapy and the change in serum syndecan-1 levels after treatment (JAAM-2)." (PMID 40740948, 2025). "For instance, elevated levels of the syndecan-1 extracellular domain had been observed in the serum of patients with sepsis, ischemia–reperfusion injury, graft-versus-host disease, and various cancers." (PMID 41357480, 2025). "In this study, serum syndecan-1 levels were measured in patients with sepsis-associated DIC treated with anticoagulant therapy, and the association between syndecan-1 levels and outcomes after sepsis-associated DIC treatment was investigated." (PMID 40740948, 2025). "A trend toward correlation was observed between sepsis-associated DIC recovery at the end of treatment and serum syndecan-1 levels (p = 0.075)." (PMID 40740948, 2025). "Levels of human polyligand proteoglycan 1 (syndecan-1), a degradation product of the glycocalyx, are associated with disease severity, mortality, and the development of DIC in patients with sepsis." (PMID 40083381, 2025). "Several additional biomarkers have been proposed for sepsis prognostication, including serum lactate, endothelin-1, angiopoietin-2, and syndecan-1." (PMID 41153844, 2025). "Among children with sepsis-associated PARDS, syndecan-1 concentrations positively correlated with total HS (r = 0.63, p < 0.01), but not total CS (r = 0.21, p = 0.26)." (PMID 37670670, 2024). "Only a transient increase at 1 h in the SDC1 mRNA levels was detected in the sepsis apoE23 treated group (P < 0.01)." (PMID 37533741, 2023). "With the administration of sulodexide, the SDC1 level was downregulated, and the survival rate of mice with sepsis improved." (PMID 37614234, 2023).
Sepsis (continued). "Here, we report a previously unidentified role of SDC1 in mediating endothelial permeability during sepsis and its prognosis." (PMID 37614234, 2023). "In an experimental sepsis model, plasma reduced mortality, lung edema and syndecan-1 shedding compared to crystalloids." (PMID 37728777, 2023). "Prior work has demonstrated that SDC1 levels are elevated in adults with sepsis with higher SDC1 levels corresponding with greater mortality risk." (PMID 37614234, 2023). "Taken together, these data suggested that sulodexide restored the survival rate and decreased SDC1 expression in the plasma of mice with sepsis." (PMID 37614234, 2023). "A systematic review of glycocalyx degradation and sepsis outcomes in ICU patients found elevated blood concentrations of syndecan-1 in patients who developed multiorgan dysfunction, renal failure, or non-survivors." (PMID 37317092, 2023). "In a previous study, upregulation of SDC1 significantly restored occludin and ZO-1 expression in sepsis." (PMID 37614234, 2023). "SDC1 appears to be involved only in the early stage (1 h time point) of sepsis in mice and transiently recovered after apoE23 treatment." (PMID 37533741, 2023). "In mice with LPS and CLP-induced sepsis, sulodexide (40 mg/kg) administration decreased the plasma levels of SDC1 and increased survival rate." (PMID 37614234, 2023). "For example, increased syndecan-1 (SYN-1) plasma levels during sepsis are correlated with the requirement for renal replacement therapy, respiratory failure, multiple organ dysfunction syndrome (MODS), and predict coagulation failure and mortality." (PMID 37081895, 2023). "Inclusion criteria required patients with sepsis and abnormal biomarkers indicating glycocalyx injury, as determined by elevated glycocalyx biomarkers (Syndecan-1 and endocan) and clinical outcome descriptions." (PMID 37842022, 2023). "As increasing evidence points towards the importance of endothelial integrity for sepsis outcome, we also analyzed serum levels of syndecan-1 at the beginning and 8 h after septic shock as a marker for endothelial glycocalyx degradation." (PMID 37264259, 2023). "We showed that SDC1-shedding caused endothelial permeability in the presence of heparinase III and sepsis conditions." (PMID 37614234, 2023). "During sepsis, constituents of the glycocalyx such as syndecan-1 and thrombomodulin are shed into the circulation, which is associated with worse patient outcomes." (PMID 37728777, 2023). "Third, sulodexide downregulated SDC1 levels in vivo and restored the survival rate of mice with sepsis." (PMID 37614234, 2023). "Syndecan-1 and -4 are particularly noteworthy, regulating inflammatory responses in contexts like myocardial injury and sepsis." (PMID 38117435, 2023). "Soluble SDC1 is found in the peripheral blood of patients with sepsis, ischemia-reperfusion injury and graft-versus-host disease." (PMID 36551905, 2022). "ANP is released by atrial myocytes in response to distension and high levels occur during hypervolemic states, such as heart failure, and syndecan-1 putatively links systemic inflammation and sepsis with excessive cardiac volume loading." (PMID 35333783, 2022). "In a rat sepsis model, the antithrombin-treatment downregulated the circulating levels of SDC-1 and HA, and improved leukocyte adhesion, and blood circulation." (PMID 36613805, 2022). "Syndecan-1, one of the biomarkers of endotheliopathy, is a predictor of mortality and sepsis in patients with trauma." (PMID 36248813, 2022). "Multiple studies show that syndecan-1 levels in sepsis correlate strongly with other markers of glycocalyx degradation." (PMID 36297099, 2022). "An animal study showed that dexamethasone treatment significantly inhibited MMP activity and reserved the expression of ZO-1 and syndecan-1 in a model of sepsis-induced vascular hyperpermeability." (PMID 35741101, 2022).
Sepsis (continued). "This study was conducted to investigate the relationship between syndecan-1, sTM, and organ dysfunction severity in septic patients, and the predictive value of these biomarkers during sepsis." (PMID 36536028, 2022). "The idea of AKI derived from endothelial injury, mainly that associated with endothelial glycocalyx damage, has gained attention and favored new studies involving syndecan-1, especially associated with AKI, including the neonatal population and in sepsis." (PMID 34846061, 2022). "A later study confirmed higher concentrations of HA, as well as syndecan-1, in sepsis patients at multiple time points of illness." (PMID 35872762, 2022). "Syndecan-1 (AUC 0.95 ± 0.02, P < 0.0001) was more valuable for prediction sepsis than was sTM (AUC 0.87 ± 0.04, P < 0.0001)." (PMID 36536028, 2022). "The suppression of syndecan-1 elevation in the early AsA group suggests that vascular endothelial cell damage suppression resulted in less sepsis-induced organ damage." (PMID 36278212, 2022). "Syndecan-1 increases in plasma during GC degradation and the level of syndecan-1 predicts mortality in sepsis." (PMID 35160072, 2022). "There was a positive correlation between the syndecan-1 level and thePELOD-2 score in the first 24 hours following the diagnosis of sepsis." (PMID 35081239, 2022). "These correlations between the syndecan-1 level and organdysfunction scores support the role of glycocalyx degradation in the morbidity oforgan failure in both adult and pediatric sepsis." (PMID 35081239, 2022). "The present study reports that a 48 h HDIVC infusion in subjects with sepsis-associated ARDS attenuated increases in 48 h cfDNA and syndecan-1 plasma levels." (PMID 36297099, 2022). "The concentration of serum syndecan-1 has been found to be significantly elevated in patients with systemic microcirculatory changes, such as sepsis, diabetes and advanced age." (PMID 36158787, 2022). "HA and syndecan-1 concentrations were also higher for the first five ICU days in severe sepsis (sepsis with acute organ dysfunction) and septic shock (sepsis with refractory hypotension despite adequate fluid loading) patients, when compared to sepsis." (PMID 35872762, 2022). "Chappel and Puskarich found that in patients who received elective surgery and those with severe sepsis, hypervolemia increased syndecan-1." (PMID 34409046, 2021). "In the present study, we aimed to define the role of the EGL and Sdc-1 protein in sepsis, using a murine sepsis model, and to test the therapeutic effects of HMW-SH." (PMID 33930030, 2021). "In an animal model of sepsis, rapid fluid administration (30 ml/kg/h) resulted in increased syndecan-1 shedding compared to the slower rate (10 ml/kg/h)." (PMID 33402229, 2021). "This research aimed to examine the effects of the limited infusion rate of fluid on glycocalyx shedding as measured by syndecan-1 in patients with sepsis-induced hypoperfusion." (PMID 33402229, 2021). "Sepsis was induced by cotton smoke inhalation followed by intranasal administration of Pseudomonas aeruginosa in female (> 6 months) Balb/c and syndecan-1 knockout mice." (PMID 33930030, 2021). "Further studies are needed to elucidate the potential utility of measuring serum syndecan-1 levels in patients with sepsis." (PMID 34557532, 2021). "Elevated circulating syndecan-1 on the first day of ICU admission was associated with persistent thrombocytopenia and lethal outcome in patients with suspected sepsis." (PMID 34557532, 2021). "To understand the role of the Sdc-1 protein in sepsis, we compared the survival of WT and Sdc-1 KO mice for 96 hours after the induction of sepsis." (PMID 33930030, 2021). "We investigated the role of endothelial glycocalyx and its component syndecan-1 protein in the pathophysiology of sepsis-induced vascular hyper-permeability and examined the therapeutic effects of high-molecular-weight sodium hyaluronate (HMW-SH)." (PMID 33930030, 2021).
Sepsis (continued). "Early death was observed in Sdc-1 KO mice; by 24 hours after the induction of sepsis, the incidence of death was significantly higher (p = 0.024) in Sdc-1 KO mice (40%) than in WT mice (10%)." (PMID 33930030, 2021). "To investigate the potential utility of evaluating serum syndecan-1 levels in patients with suspected sepsis, we first analyzed the relationship between serum syndecan-1 and fatal outcome." (PMID 34557532, 2021). "As a consequence, circulating syndecan-1 levels can become increased in patients with sepsis, especially in those with multiple organ failure." (PMID 34557532, 2021). "Consistent with previous studies, we found that syndecan-1 was significantly increased in the group of sepsis patients with DIC." (PMID 34707618, 2021). "This survival study result is not consistent with the result obtained from the skin thermal injury-induced sepsis model, where death was delayed in septic Sdc-1 KO mice." (PMID 33930030, 2021). "The present research has shown that SDC-1 was elevated in many diseases such as sepsis, diabetes, trauma, and surgery, and the degradation of glycocalyx was considered to be the cause of microcirculation dysfunction." (PMID 34970076, 2021). "In the present study, we found that several endothelial dysfunction and injury biomarkers, including angiopoietin-2, endocan, sVE-cadherin, and syndecan-1, were higher in sepsis patients who developed severe AKI." (PMID 33541396, 2021). "Nevertheless, our model focused on the early phase of sepsis (< 24 h) whereas the increase of syndecan-1 has been described to be elevated at day 2 in septic patients, but not at admission, suggesting a time-dependent variation of this marker." (PMID 32546181, 2020). "The mean syndecan-1 levels for both the surgery group (50.5 ± 46.9 ng/mL) and sepsis group (160 ± 109 ng/mL) were higher compared to controls (20.5 ± 5.05 ng/mL) (p = 0.01 and p < 0.001, respectively)." (PMID 30654825, 2019). "Several previous reports have revealed the relationships of syndecan-1 with severe diseases, such as acute kidney injury, chronic kidney disease, cardiac arrest, cardiovascular disease, and sepsis." (PMID 31462009, 2019). "In fact, serum syndecan-1 was used as an endothelial injury marker in recent clinical studies of sepsis." (PMID 31462009, 2019). "Syndecan-1 levels have been studied previously in major trauma and/or haemorrhagic shock, and sepsis." (PMID 29337920, 2018). "This is consistent with glycocalyx shedding which predicts sepsis outcome as increased free syndecan-1, a heparan sulphate protein, in plasma indicates poor prognosis in sepsis." (PMID 29717213, 2018). "Glycocalyx dysfunction and syndecan-1 shedding have been described in a variety of clinical pathophysiologic processes, including sepsis, hemorrhagic shock, atherosclerosis, acute coronary syndrome, renal disease, diabetes, and hypervolemia." (PMID 28986821, 2017). "In severe sepsis, high concentrations of syndecan-1 in plasma were defined as being 12 times higher than the baseline level reported in the present study." (PMID 28830365, 2017). "Several studies have demonstrated elevated syndecan-1 levels as a marker of glycocalyx degradation in patients with sepsis." (PMID 28986821, 2017). "In this study, levels of syndecan-1 have been evaluated in 104 patients suffering from severe sepsis or septic shock, in 28 patients after major abdominal surgery and in 18 healthy young volunteers without any signs of infection." (PMID 27699168, 2016). "Soluble Sdc1 levels at term (median 1415 ng/mL) are similar to those reported during sepsis, and represent an approximate 50-fold increase over the postpartum levels." (PMID 27299886, 2016). "Levels of syndecan-1 were markedly elevated in the sepsis and the surgery group, compared with the control group." (PMID 27699168, 2016).
Sepsis (continued). "Circulating soluble Sdc1 concentrations can be increased by excess reactive oxygen species or inflammatory stimuli, as exemplified by the extremely high values observed with sepsis." (PMID 27299886, 2016). "In fact, in addition to these findings, syndecan-1 correlates with coagulopathy and increased mortality in sepsis patients." (PMID 27699168, 2016). "In an experimental model of sepsis, high levels of TNF-α were associated with reduced expression of syndecan 1 and altered composition of hyaluronan and sialic acids." (PMID 25887223, 2015). "Other investigators have examined shedding of syndecan-1 after sepsis, surgery, and ischemia/reperfusion, however, syndecan-1 levels in the current study markedly exceed those previously reported." (PMID 21886795, 2011). "SDC1 reflects endothelial glycocalyx degradation, which is known to occur early in sepsis and may precede functional renal impairment." (PMID 40806992, 2025). "Previous studies have indicated that syndecan-1 is a marker for the prognosis and severity of sepsis, acute kidney injury, trauma, and heart failure, suggesting that it may serve as a predictive biomarker of mortality in critically ill patients." (PMID 40740948, 2025). "In the early phase of sepsis, inflammatory stimuli and endothelial injury may trigger the release of HS-rich SDC1 ectodomains from the cell surface." (PMID 41293540, 2025). "Specifically, patients who did not recover from sepsis-associated DIC exhibited a ≥ 30% increase in serum syndecan-1 levels after anticoagulant therapy, while no such increase was observed in the recovery group." (PMID 40740948, 2025). "Children with sepsis-associated PARDS exhibited higher plasma levels of heparan sulfate disaccharides and syndecan-1, suggesting that EGCX degradation biomarkers may provide insights into endothelial dysfunction and PARDS pathobiology." (PMID 37670670, 2024). "We identified that circulating HS disaccharides and syndecan-1 levels were higher in mechanically ventilated children with sepsis-associated PARDS relative to children without PARDS." (PMID 37670670, 2024). "During sepsis, immune cells and their inflammatory products activate the endothelium that result in shedding of its ‘fuzz-like’ glycocalyx, indicated by serum elevations in syndecan-1 and soluble-thrombomodulin." (PMID 38811967, 2024). "Circulating HS disaccharides and syndecan-1 were increased in sepsis-associated PARDS relative to children without PARDS." (PMID 37670670, 2024). "Syndecan-1 and endoglin are crucial components of the glycocalyx, the protective layer lining the luminal surface of ECs; their degradation contributes to microcirculatory dysfunction in sepsis." (PMID 38921594, 2024). "Previous studies have shown that SDC1 is a prognostic marker in patients with sepsis." (PMID 37614234, 2023). "In the sepsis model, SDC1 expression was lower than in the control group." (PMID 37614234, 2023). "Sulodexide helped preserve SDC1 expression in the lung tissues of the sepsis model." (PMID 37614234, 2023). "Zhou and colleagues reported that serum soluble thrombomodulin(sTM) and syndecan-1 could be potential biomarkers for the early diagnosis of sepsis." (PMID 37575274, 2023). "Together, these data may suggest that in the setting of sepsis, shedding of SDC1 from the endothelial glycocalyx may increase endothelial permeability through a reduction in ZO-1/VE-cadherin expression." (PMID 37614234, 2023). "In addition, sulodexide administration attenuated SDC1 shedding and improved survival outcomes in murine sepsis." (PMID 37614234, 2023). "First, we measured SDC1 levels in the plasma of mice with sepsis." (PMID 37614234, 2023). "In addition, many reports have confirmed that the serum levels of glycocalyx-related components, such as SDC-1, a marker of glycocalyx damage in endothelial cells, were increased in patients with sepsis." (PMID 35246004, 2022).